GRK3 (G protein-coupled receptor kinase 3)
Diseases named in the same sentence as GRK3 in open-access papers (continued):
Sharing a sentence is not in itself a finding about the gene and the disease.
tumor (13 papers, 2011 to 2025). "Significant associations were observed between aberrant GRK3 expression and advanced cancer biology, which was indicated by tumor invasion depth, lymph node metastasis, and distant metastasis." (PMID 29445249, 2017). "Univariate analyses indicated that AJCC stage, depth of tumor invasion, the presence of lymph node involvement, distant metastasis, histologic differentiation, and GRK3 expression pattern were significantly associated with DFS and OS." (PMID 29445249, 2017). "The sprawling, less dense tumor mass and increased chemotactic ability of the GRK3-deficient 66cl4-luc cells suggest that more motile cells within the primary tumor ultimately result in the increased distant metastases." (PMID 27049755, 2016). "Our results revealed significant associations between the GRK3 overexpression and the following clinicopathological features: American Joint Committee on Cancer Stage, depth of tumor invasion, lymph node involvement, distant metastasis, and histologic differentiation." (PMID 29445249, 2017). "Previous studies have indicated that GRK3 can inhibit the proliferation of tumour cells and smooth muscle contraction." (PMID 41446394, 2025). "GRK3 OE significantly increased tumor growth but LD2 inhibited tumor growth in the PDX model and dramatically suppressed peritoneal metastases induced by GRK3 OE." (PMID 35996148, 2022). "We found tumor cell invasion and colony formation were significantly increased in GRK3 overexpressed MKN45 cells compared to MKN45-GFP control cells." (PMID 35996148, 2022). "Tumor tissues from 47% of patients showed higher expression or overexpression of GRK3 (interpreted score of 2 in 40% of patients and interpreted score of 3 in 7% of patients)." (PMID 35281865, 2022). "Further analysis revealed the overexpression of GRK3 in GACs of patients with diffuse type, lymph node metastases, and those with higher tumor stage." (PMID 35996148, 2022). "Tumor burden, tumor volume, and tumor weight at end of experiments were also significantly larger in GRK3 OE group than NC group." (PMID 35996148, 2022). "We collected paired primary tumor cells and PC cells from the same mouse and determined GRK3 expression using Western blotting." (PMID 35996148, 2022). "Further, overexpression of GRK3 in MKN45 cells significantly increased tumor cell growth at any FBS concentration used (0–5%) media in 6 day and and increased tumor sphere formation." (PMID 35996148, 2022). "Expression of GRK3 in tumor tissues in a large GAC cohort (n = 876) significantly associated with poor survival as well as a higher risk of death (P = 1.2e-08; hazard ratio = 1.74, confidence interval 1.43–2.11, kmplot.com)." (PMID 35996148, 2022). "The clinical significance of GRK3 expression in different tumor types varies drastically and seems context-dependent." (PMID 35996148, 2022). "LD2, a novel GRK3 inhibitor, actively reduced tumor cell growth, invasion, and tumor sphere formation in vitro in multiple GAC cell models and in vivo in a GAC PDX model with high GRK3 and YAP1 expression." (PMID 35996148, 2022). "We then elucidated the functional role of GRK3 in promoting tumor growth and metastases using genetic approaches." (PMID 35996148, 2022). "Over the three-week of inoculation period, tumor growth was faster in GRK3 OE group compared to NC group." (PMID 35996148, 2022). "GRK3 overexpression, depth of tumor invasion, lymphatic metastasis, distant metastasis, TNM stage, degree of differentiation, and vascular invasion were significantly correlated with disease-free survival." (PMID 35281865, 2022). "Specifically, GRK3 was not expressed at all in tumor tissues from 8% of patients (interpreted score of 0), and tumor tissues from 44% of patients showed weak and localized GRK3 expression (interpreted score of 1)." (PMID 35281865, 2022). "The analysis of human genetic data confirms potential involvement of GRK3 in tumor progression and metastasis." (PMID 27049755, 2016).
tumor (continued). "Across large datasets, decreased GRK3 expression correlated better with tumor (vs normal breast) than changes in CXCR4 expression." (PMID 27049755, 2016). "In vivo bioluminescent imaging of 66cl4-luciferase tumors demonstrates an apparently larger, more diffuse tumor arising from GRK3-knockdown cells despite similarity of cellular radiance quantification." (PMID 27049755, 2016). "Moreover, non-visual GRK member investigations have shown that GRK5 and GRK3 act completely differently in a variety of tumor types." (PMID 38638965, 2024). "GRK3 shows varied expression levels and functions in different tumor types." (PMID 35996148, 2022). "Further study on the role of SLAMF9 and GRK3 in the microenvironment and tumor progression of laryngeal chondrosarcoma may provide clues for laryngeal chondrosarcoma pathogenesis and potential new therapeutic targets." (PMID 34931260, 2022). "Similarly, overexpression of GRK3 wild type cDNA in KATO III cells significantly increased its tumor sphere formation, invasion, colony formation and proliferation, which was reduced in its kinase dead mutant form." (PMID 35996148, 2022). "In addition, tumor microvessel density significantly increased when GRK3 was overexpressed in tumor cells, suggesting that GRK3 promoted angiogenesis." (PMID 35281865, 2022). "In summary, the expression level of GRK3 in different cancers suggests that it may act as an oncogene or a tumor suppressor gene in different cancers, depending on the tissue type, cancer type, and cancer stage." (PMID 35281865, 2022). "Moreover, we have demonstrated that downregulation of GRK3 is also sufficient to decrease primary tumor growth and induce apoptosis phenotype of importance." (PMID 29445249, 2017). "The analysis determined that primary tumor burden was not significantly different, albeit slightly increased on average, in GRK3-deficient tumors compared to controls throughout the 6-week period." (PMID 27049755, 2016). "Immunohistochemistry staining (IHS) showed that the expressions of GRK2 and GRK3 were significantly lower in tumor than in adjacent tissues, correlated with disease-free survival and overall survival (OS) in HCC patients, while the GRK6 might mediate a tumor growth signaling." (PMID 35769816, 2022). "In addition, Kaplan-Meier curves with a log-rank test and Cox proportional hazards model analysis indicated that the patients with positive tumor GRK3 expression had a lower five-year overall survival and disease-free survival rate than patients with negative GRK3 expression." (PMID 29445249, 2017). "In addition, overexpressing GRK3 promoted LNCaP cell-derived primary tumor growth in vivo." (PMID 27191986, 2016). "One potential explanation is that the density of the tumor might be affected by the mobility of the individual GRK3-deficient tumor cells or by the recruitment of non-tumor cells into the tumor site." (PMID 27049755, 2016). "To evaluate the anti-tumor activity of LD2 in vivo, we used GA0518 patient-derived PC cells which have high GRK3 and YAP1 expression." (PMID 35996148, 2022). "To further demonstrate the effect of GRK3 in the PC-related mouse metastatic model (the tumor microenvironment is somewhat similar to that of metastatic human GAC), we injected MKN45 GFP control (NC) cells and GRK3 OE cells intraperitoneally in SCID mice." (PMID 35996148, 2022). "These researchers transplanted GRK3-knockdown cells into the prostate of SCID mice and found a significant decrease in tumor proliferation and metastasis." (PMID 35281865, 2022). "Of note, GRK3 overexpression in MKN45 and KATO III significantly increased tumor sphere formation in both GAC cells, which were dramatically suppressed by LD2 treatment in a dose dependent manner." (PMID 35996148, 2022). "Co-immunofluorescent staining (IF) further validated that expression of GRK3 and SOX9 was dramatically increased in tumor tissues from the GRK3 OE group, compared to the NC group." (PMID 35996148, 2022).
tumor (continued). "Overexpression of GRK3 was closely correlated with AJCC stage (P = 0.001), depth of tumor invasion (P < 0.001), lymph node involvement (P = 0.004), distant metastasis (P = 0.016), and histologic differentiation (P = 0.004)." (PMID 29445249, 2017). "GRK3 are highly expressed in different cellular types of the immune system and are important regulators of inflammation; the altered expression of GRK3 may play a pivotal role in cell motility in pathological situations related to inflammation or tumor progression." (PMID 29445249, 2017). "Similar results were seen in the analysis of the TCGA database where GRK3 and GRK5 again showed lower expression levels in tumor cells compared to normal breast tissue." (PMID 27049755, 2016). "Importantly, we identified a novel GRK3 inhibitor, LD2, through a chemical library screen and demonstrated its strong anti-tumor activity in vitro and in vivo in patient-derived PC cells with high GRK3 and YAP1 expressions." (PMID 35996148, 2022). "By IHC and immunofluorescent staining, we found that GRK3 expression was higher in tumor tissues than in adjacent normal tissues and even higher in PC cells." (PMID 35996148, 2022). "Overall, our functional studies using pharmacologic and genetic modulations of GRK3 revealed that GRK3 plays an important oncogenic role in GAC, as the inhibition of GRK3 reduced GAC's aggressive phenotypes, including cell proliferation, tumor sphere formation, and invasion." (PMID 35996148, 2022). "Immunohistochemistry revealed that GRK3 expression was higher in tumor tissues than in nontumor tissues." (PMID 35281865, 2022). "In contrast, Knockdown (KD) of GRK3 in GA0518 patient-derived cells with relatively high GRK3 level significantly decreased cell growth in two individual KD clones and reduced colony formation and tumor sphere compared to control cells." (PMID 35996148, 2022). "Importantly, we identified a novel GRK3 inhibitor LD2, which demonstrated strong anti-tumor activity in vitro and in vivo in the PDX model." (PMID 35996148, 2022). "We observed that the overexpression of GRK3 was closely correlated with American Joint Committee on Cancer Stage, AJCC (P = 0.001), depth of tumor invasion (P < 0.001), lymph node involvement (P = 0.004), distant metastasis (P = 0.016), and histologic differentiation (P = 0.004)." (PMID 29445249, 2017). "G protein coupled receptor kinase 3 (GRK3) is a negative regulator of CXCR4 activity, and we show that GRK expression correlates with tumorigenicity, molecular subtype, and metastatic potential in human tumor microarray analysis." (PMID 27049755, 2016). "The effects of GRK3 modulation appear to be specific to chemokine-mediated migration behaviors without influencing tumor cell proliferation or survival." (PMID 27049755, 2016). "In addition, immunoblotting also showed that GRK3 expression was higher in tumor tissues than in nontumor tissues." (PMID 35281865, 2022). "Because the GPCR CXCR7 also binds to CXCL12 and has been shown to have a potential a role in tumor growth and metastasis, we also compared CXCR7:GRK3 expression ratios, but they did not correlate with invasive phenotype." (PMID 27049755, 2016). "Furthermore, we evaluated expression of GRK3, YAP1, and SOX9 and cell proliferation marker Ki67 in the tumor tissues of mice treated with or without LD2 using IF." (PMID 35996148, 2022).
cancer (8 papers, 2016 to 2023). A tumor composed of atypical neoplastic, often pleomorphic cells that invade other tissues. "The anti-cancer effects of GRk3 were also checked in Eca109 and KYSE150 cell lines (both esophageal squamous carcinoma cell lines), and it was observed that GRk3 suppressed proliferation and colony formation for both cell types." (PMID 38139116, 2023). "At present, only few studies have discussed the correlation between GRK3 and cancer prognosis, and their conclusions are inconsistent." (PMID 35281865, 2022). "Taken together, it is plausible that GRK3 functions as a cancer-promoting factor by promoting proliferation, although the molecular mechanisms need to be further elucidated." (PMID 29445249, 2017). "Our results reveal that GRK3 is a direct target of CREB, which suggests a positive correlation between CREB and GRK3 expression in human cancer cells and tissues." (PMID 27191986, 2016). "We have presented several lines of evidence suggesting that kinase activity of GRK3 is critical for its roles in cancer." (PMID 27191986, 2016). "Previous studies have reported that GRK3 may act as an oncogene or a tumor suppressor gene in different cancers, depending on different tissues types, cancer types, and cancer stages." (PMID 35281865, 2022). "Importantly, we found that LD2 suppresses GRK3-mediated oncogenic activity in GAC cell lines and patient PC cells, whose inhibitory effects are less dramatic in GRK3-low cancer cells." (PMID 35996148, 2022). "GRK3 may promote cancer development by facilitating GPCR-mediated oncogenic functions through phosphorylation of some GPCRs." (PMID 35996148, 2022). "In contrast, GRK3 expression is significantly increased in other cancers." (PMID 35281865, 2022). "The expression of G protein-coupled receptor kinase 3 (GRK3) has been reported in various cancers." (PMID 35281865, 2022). "Hence, more studies are required to clarify the correlation between GRK3 and cancer prognosis." (PMID 35281865, 2022). "Therefore, the roles of GRK3 in various cancers are likely context dependent." (PMID 35996148, 2022). "Therefore, it can be speculated that the CREB/GRK3 axis may be active in wide range of cancer cells and biological contexts." (PMID 27191986, 2016). "Deregulation of G protein-coupled receptor kinase 3 (GRK3), which belongs to a subfamily of kinases called GRKs, acts as a promoter mechanism in some cancer types." (PMID 29445249, 2017). "Thus, we propose that high CXCR4 on the cell surface, combined with decreased intracellular regulatory GRK3, leads to impaired receptor internalization and more active CXCL12-mediated migration of the cancer cell." (PMID 27049755, 2016).
cardiovascular diseases (1 paper, 2019). "Three different GRK isoforms (GRK2, GRK5, and GRK3) and two β-adrenoceptors (β1-AR and β2-AR) are present in peripheral blood mononuclear cells (PBMC) and their expression changes as a consequence of the hemodynamic and neurohumoral alterations that occur in some cardiovascular diseases." (PMID 30837872, 2019).
GRK3 also shares sentences with these, for which no sentence is quoted: bipolar disorder (2 papers); Dyskinesia (1); esophageal cancer (1); hepatocellular carcinoma (1); Hypertension (1); immune deficiency (1); Kaposi's sarcoma (1); leukocytosis (1); Lewis lung carcinoma (1); liver cancer (1); lymphoma (1); Myocardial fibrosis (1); Paget’s Disease of Bone (1); Parkinson disease (1); peritoneal carcinoma (1); triple-negative breast carcinoma (1); type 2 diabetes (1).